MIR1199 (microRNA 1199)
Synonyms: hsa-mir-1199
Gene: MicroRNA gene on chromosome 19 (14,073,361 to 14,073,479, forward strand). Ensembl gene ENSG00000284081.
Homologues: Orthologues: chimpanzee ptr-mir-1199 (100% identical).